LEPR (leptin receptor)
Diseases named in the same sentence as LEPR in open-access papers (continued):
Sharing a sentence is not in itself a finding about the gene and the disease.
triple-negative breast carcinoma (5 papers, 2014 to 2022). An invasive breast carcinoma which is negative for expression of estrogen receptor (ER), progesterone receptor (PR), and human epidermal growth factor receptor 2 (HER2). "In fact, an LEPR antagonist was recently tested in a preclinical murine model of triple-negative breast cancer and showed improved survival benefits." (PMID 35115495, 2022). "The expression of LEPR is also necessary for maintaining cancer stem cell-like and metastatic properties in triple-negative breast cancer." (PMID 35223490, 2022). "The leptin receptor has been reported to be necessary for maintaining the cancer cell's stem cell-like properties in triple-negative breast cancer cells." (PMID 25948792, 2015). "SHP2 has an oncogenic role in triple-negative breast cancer, and functions as an adaptor protein in LEPR signalling to ERK1/2." (PMID 25482303, 2014). "Our data corroborates the recent finding that leptin receptor expression is required to maintain cancer stem-like properties in triple-negative breast cancer cells." (PMID 25482303, 2014).
acute myeloid leukemia (4 papers, 2018 to 2026). Acute myeloid leukemia (AML) is a group of neoplasms arising from precursor cells committed to the myeloid cell-line differentiation. "In leukemia, a previous study reported that fasting could slow the progression of acute lymphoblastic leukemia (ALL) but not acute myeloid leukemia (AML) by activating the protein PR/SET domain 1 (PRDM1)-mediated leptin receptor and downstream signaling." (PMID 35246220, 2022).
Anorexia (4 papers, 2020 to 2024). Lack of desire to eat (loss of appetite). "Another acute-phase protein, ORM1, is a potential contributor to anorexia through its role in the excessive activation of hypothalamic leptin receptor signaling." (PMID 39727925, 2024). "The role of hypothalamic astrocyte LepR signaling in energy homeostasis is well established in previous studies: knockdown of LepR in the hypothalamus leads to alterations in neural circuitry and attenuates leptin-induced anorexia in mice." (PMID 32152264, 2020).
Arthritis (4 papers, 2013 to 2023). Inflammation of a joint. "In preclinical setting, both the leptin deficient and leptin receptor deficient mice exhibited a delayed resolution of arthritis, and leptin supplementation was reported to ameliorate arthritis." (PMID 27041823, 2016). "In mice with antigen-induced arthritis, impaired leptin signaling via leptin or leptin-receptor deletion attenuates arthritis severity, demonstrating that leptin plays a direct role in RA progression." (PMID 23922673, 2013). "On the other hand, in the proliferative arthritis model of zymosan-induced arthritis (ZIA), leptin appears to have a different function, as histopathology showed that ob/ob mice and mice with leptin receptor deficiency (db/db) had delayed arthritis resolution and more joint damage than controls." (PMID 38001998, 2023).
autism (4 papers, 2015 to 2023). Persistent deficits in social interaction and communication and interaction as well as a markedly restricted repertoire of activity and interest as well as repetitive patterns of behavior. "Partial and whole uniparental disomy of chromosome 1 has been reported in autism, fumarase deficiency, Stargardt disease, Pelizaeus- Merzbacher-like disease, leptin receptor deficiency, rhizomelic chondrodysplasia punctata type 2 and CD45-deficient severe combined immunodeficiency." (PMID 25872961, 2015). "Interestingly, miR-153-3p has also been reported to target the leptin receptor and alleviate some autistic symptoms in the mouse valproate model of autism." (PMID 38071324, 2023). "The present study also demonstrated that LEPR is a target gene of miR-153 in autism." (PMID 30975733, 2019). "RT-qPCR and Western blot analysis were performed to detect the expression of miR-153, LEPR, JAK, and STAT in order to investigate the mechanisms and functions of miR-153 in autism." (PMID 30975733, 2019).
autoimmune disease (4 papers, 2017 to 2021). A disorder resulting from loss of function or tissue destruction of an organ or multiple organs, arising from humoral or cellular immune responses of the individual to their own tissue constituents. "Above all, LEPR plays a significant role in both the adaptive and innate immune responses and is closely associated with autoimmune diseases." (PMID 33988300, 2021). "Thus, LEP and LEPR gene polymorphisms might influence the production and activity of inflammatory cytokines and thereby play a role in the development of various autoimmune diseases." (PMID 28244652, 2017). "Both leptin excess and leptin deficiency, as well as leptin resistance, are correlated with different human pathologies, such as autoimmune diseases and cancers, making leptin and leptin receptor important drug targets." (PMID 34356668, 2021). "Based on leptin’s role in autoimmune diseases and cancer, several leptin and leptin receptor (LR) antagonists have been developed, but these intrinsically lead to unwanted weight gain." (PMID 30659329, 2019).
COVID-19 (4 papers, 2021 to 2025). A disease caused by infection with severe acute respiratory syndrome coronavirus 2. "Altogether, our data suggests that modulating the leptin receptor signaling could, hypothetically, help restore immune homeostasis in T2DM patients, which might mitigate some of the complications associated with COVID-19 in this patient population." (PMID 40125513, 2025). "Our analysis also showed that LEPR is downregulated in COVID-19." (PMID 36589459, 2022).
heart failure (4 papers, 2013 to 2025). Inability of the heart to pump blood at an adequate rate to meet tissue metabolic requirements. "A few anti-LepR antibodies have been generated and tested in models of heart failure, multiple sclerosis, and autoimmune encephalomyelitis." (PMID 24587106, 2014).
immune deficiency (4 papers, 2018 to 2023). "Previous reports have confirmed that leptin (acts via leptin receptor) is negatively correlated with the production of regulatory T cells and hence associated with immune deficiency." (PMID 29503661, 2018). "Therefore, the elevated expression of leptin/leptin receptor in EMS prompts immune deficiency which may induce MS." (PMID 29503661, 2018).
liver cancer (4 papers, 2015 to 2021). An epithelial or non-epithelial malignant neoplasm that arises from the liver. "The underlying mechanisms of LEPR in liver cancer metastasis were addressed." (PMID 33799880, 2021). "We discovered that LEPR was highly expressed in liver cancer tissues, and the expression of LEPR in Hca-F cells was higher than that in Hca-P cells." (PMID 33397392, 2021). "In order to investigate the role of LEPR in tumorigenesis, we examined the liver cancer database Oncomine to evaluate the differential expression of LEPR." (PMID 33397392, 2021). "In addition, leptin receptor expression is relatively high in liver cancer, indicating the potential pathological roles of this axis in cancers." (PMID 33799880, 2021). "In this study, we demonstrated the overexpression of LEPR in liver cancer tissue." (PMID 33397392, 2021). "Together, these results confirmed that that LEPR expression is enriched in liver cancer." (PMID 33397392, 2021). "Collectively, our experiments show that hepatic LEPR exerts a compensatory function in IL-6Rα-deficient mice in DEN-induced liver cancer development largely independent of changes in whole body metabolism." (PMID 30224299, 2018). "Hepatic LEPR, whole body IL-6Rα, and combined deficiencies did not alter body composition, insulin sensitivity, and glucose tolerance in the DEN model of liver cancer in vivo." (PMID 30224299, 2018).
liver disease (4 papers, 2015 to 2021). "Serum LEP level and LEPR Q223R gene polymorphism were determined in 300 patients with liver disease categorized equally into five groups’ healthy volunteers, patients with hepatitis C (HCV), patients with non-alcoholic steatohepatitis (NASH), liver cirrhosis and HCC." (PMID 33369452, 2020). "Conversely, the expression of the down-regulated genes, including many metabolism- (e.g., leptin receptor and insulin receptor substrate 2) and mitochondria-related genes, decreased with the progression of liver disease, and BCAA supplementation rescued this down-regulation." (PMID 28212548, 2017). "Association between variants of LEPR rs1137100 and rs1137101 with risk of NAFLD was also revealed in Asian group but only G allele of t rs1137100 was associated with a less severe form of liver disease in patients with NAFLD." (PMID 26042596, 2015).
liver fibrosis (4 papers, 2014 to 2024). "Thus, leptin acts as a pro-fibrogenic adipokine, as it positively regulates Collagen α1 and increases the differentiation of HSCs, which expresses leptin receptors (LepR), a factor that leads to the establishment of liver fibrosis." (PMID 38612504, 2024). "Additionally, mice receiving the treatment of recombinant leptin promoted fibrogenic response, whereas leptin receptor-deficient rats failed to develop liver fibrosis." (PMID 29436483, 2018).
oral squamous cell carcinoma (4 papers, 2013 to 2021). "The purpose of this study was to assess the LEPR gene Gln223Arg polymorphism (rs1137101) in oral squamous cell carcinoma (OSCC) and in potentially malignant oral lesions (PMOL) in comparison to normal oral mucosa in a Brazilian population." (PMID 26034683, 2014). "In this study, we hypothesized that variants of the LEPR Gln223Arg polymorphism can be associated with oral squamous cell carcinoma and PMOL." (PMID 26034683, 2014).
osteoarthritis (4 papers, 2010 to 2022). A noninflammatory degenerative joint disease occurring chiefly in older persons, characterized by degeneration of the articular cartilage, hypertrophy of bone at the margins and changes in the synovial membrane. "In bone-derived MSCs from patients with osteoarthritis, we also identified a lower expression of the leptin receptor, a marker of MSCs that present a major source of MSCs in the adult bone marrow." (PMID 32245507, 2020). "For example, recent studies have shown that mice deficient in leptin or the leptin receptor undergo extreme weight gain but exhibit no changes in osteoarthritis." (PMID 20604941, 2010). "Since leptin receptor is a marker of stem cells in the adult bone marrow, the finding indicates the exhaustion of skeletal muscle and bone-derived BMSC is a sign of osteoarthritis." (PMID 35578312, 2022).
papillary thyroid cancer (4 papers, 2011 to 2020). "An endogenous anti-appetite factor, leptin has also been shown to support the growth of certain tumors, including papillary thyroid carcinoma, that express the leptin receptor." (PMID 32645835, 2020). "We also note that papillary thyroid carcinoma cells may express the leptin receptor, and circulating leptin from adipocytes may stimulate tumor cell proliferation." (PMID 32645835, 2020). "Finally, we have also pointed out in the current review that leptin may be a trophic factor for papillary thyroid carcinoma, a form of cancer known to express the leptin receptor." (PMID 32645835, 2020).
prostate tumor (4 papers, 2012 to 2020). "Both AdipR1/2 and LepR are expressed in prostate tumor tissues and prostate tumor cell lines, but the distribution is entirely different." (PMID 30013512, 2018). "Therefore, there is increased availability of leptin for binding to the long leptin receptor signaling isoform in the prostate tumor cell membrane." (PMID 22792137, 2012). "Analysis of RNAseq data for 52 normal prostate (control) and 498 prostate adenocarcinoma obtained from TCGA database, revealed that LEP, LEPR, JAK2 and STAT3 are statistically significant downregulated in prostate tumors in relation to normal (control) prostate." (PMID 31671654, 2019).
Alström syndrome (3 papers, 2019 to 2023). "These consequences are related to proopiomelanocortin (POMC), proprotein convertase subtilisin/kexin type 1 (PCSK1), or leptin receptor deficiency (LEPR), as well as other rare genetic diseases, including BBS and Alström syndrome." (PMID 37888071, 2023).
Alzheimer disease (3 papers, 2017 to 2022). A progressive, neurodegenerative disease characterized by loss of function and death of nerve cells in several areas of the brain leading to loss of cognitive function such as memory and language. "This is consistent with previous data obtained from the Alzheimer's Disease Neuroimaging Initiative (ADNI) cohort study, which showed decreased LepR immunoreactivity in brains from individuals suffering severe AD, and similarly the LepR mRNA was also reduced only in the old AD transgenic mice." (PMID 28442988, 2017).
benign prostatic hyperplasia (3 papers, 2019 to 2024). A non-cancerous nodular enlargement of the prostate gland. "In other studies, using RT-PCR method, the following LEPR variants were expressed in tissue samples from benign prostatic hyperplasia (BPH): variants 4 and 2 (in all five samples studied), var." (PMID 31671654, 2019). "These in vivo and in vitro ROCK1 knockdown data confirmed that reduced ROCK1 signaling inhibits the recruitment and differentiation of LepR+ cells in prostatic hyperplasia." (PMID 38711089, 2024). "Furthermore, LepR-tdTomato mice were utilized to investigate whether aberrant activation of TGF-β is involved in the recruitment of LepR+ MSCs during prostatic hyperplasia." (PMID 38711089, 2024).
bipolar disorder (3 papers, 2022 to 2024). A disorder of the brain that causes unusual shifts in mood, energy, activity levels and the ability to carry out day-to-day tasks. "The main finding of this study is that the following adipokines correlated with MS in the bipolar depression women group: visfatin, S100B, and leptin had a positive correlation, whereas adiponectin, leptin-receptor, and adiponectin/leptin ratio showed a negative correlation." (PMID 37960185, 2023).
Breast Invasive Carcinoma (3 papers, 2022 to 2026). "An analysis of LEPR mRNA expression across various molecular subtypes of BC using GEPIA was conducted on 1080 human BC tumors from The Breast Invasive Carcinoma (TCGA, PanCancer Atlas)." (PMID 41562922, 2026). "LEPR shows differential expression among breast invasive carcinoma stages, while ITLN1 shows differential expression in stage II only." (PMID 41221514, 2025).
cholestasis (3 papers, 2010 to 2022). Impairment of the bile flow caused by obstruction within the liver, or outside the liver in the bile duct system. "In a former study of our group, we could demonstrate that leptin receptor serum levels were associated with parameters of inflammation (e.g., PCT) and cholestasis indicating poor ICU and overall survival." (PMID 35054232, 2021). "Interestingly, leptin-receptor showed significant correlations to various parameters reflecting cholestasis such as bilirubin, conjugated bilirubin, gamma-glutamyltranspeptidase, and alkaline phosphatase activity." (PMID 20871818, 2010).
epilepsy (3 papers, 2018 to 2024). A brain disorder characterized by episodes of abnormally increased neuronal discharge resulting in transient episodes of sensory or motor neurological dysfunction, or psychic dysfunction. "Supporting our findings, a positive association between weight gain and the LEPR rs1137101 SNP was also demonstrated in a study on 212 epilepsy patients receiving VPA." (PMID 39539630, 2024). "Weight gain, a common adverse reaction of VPA, has been associated with leptin receptor (LEPR) and ankyrin repeat kinase domain containing 1 (ANKK1) gene polymorphisms in a cohort of Han Chinese people with epilepsy." (PMID 28082152, 2018). "Furthermore, the observed associations between rs1137101 (LEPR) and rs4480 variants (SOD2) with weight gain and hair loss further highlight the importance of personalized medicine in managing epilepsy." (PMID 39539630, 2024). "Furthermore, a cohort study involving 212 Han Chinese patients with epilepsy treated with VPA identified associations between weight gain and polymorphisms in the leptin receptor (LEPR) and ankyrin repeat kinase domain containing 1 (ANKK1) genes." (PMID 39539630, 2024).
gallbladder cancer (3 papers, 2018 to 2021). "Findings in human gallbladder cancer suggested the requirement of leptin-leptin receptor signaling axis activation in cancer progression because leptin increased cell proliferation via the leptin receptor." (PMID 33799880, 2021). "Leptin and its receptor LEPR promote the proliferation and metastasis of gallbladder carcinoma, which may participate in the regulation of MMPs and the VEGF family through the SOCS3/JAK2/STAT3 pathways." (PMID 33397392, 2021). "In human gallbladder cancer, the experiment result also demonstrated the function of leptin in promoting cell proliferation through leptin receptor (OB-Rb), revealing the requirement of leptin receptor in leptin-dependent cancer progression." (PMID 29682217, 2018).
gastric cancer (3 papers, 2015 to 2021). A primary or metastatic malignant neoplasm involving the stomach. "Recent studies indicate that LEPR is highly abundant in many cancers, including oesophageal, breast, gastric, colon and gastric cancer." (PMID 33397392, 2021). "The siRNA against leptin-receptor was transfected into three stomach cancer cell lines, and western blot for caspase 3 was performed." (PMID 26147886, 2015). "Immunohistochemistry for leptin signalling-related proteins (leptin, leptin-receptor, pSTAT3, ERK, pAkt, mTOR and HIF-1 alpha), and in situ hybridization for EBV-encoded small RNAs was performed in 343 cases of gastric carcinomas." (PMID 26147886, 2015). "The present study highlighted that leptin-receptor expression can be an independent poor prognostic factor in specific subsets of gastric carcinomas." (PMID 26147886, 2015). "In 207 advanced gastric carcinomas, leptin-receptor expression was correlated with a poor survival of patients in univariate and multivariate analyses (P < 0.05)." (PMID 26147886, 2015). "In three gastric carcinoma cell lines, transfection of siRNA against leptin-receptor resulted in a remarkable increase of cleaved caspase 3 (p11, p17 and p20 subunits), comparing to each original cells and each scrambled siRNA-transfected cells." (PMID 26147886, 2015). "Expression of leptin and leptin-receptor were observed in 37% (128/343) and 58% (198/343) of total gastric carcinomas, respectively." (PMID 26147886, 2015). "The results indicated that LEPR methylation levels were significantly lower in tumor samples than in adjacent (5 cm away) nontumor samples, suggesting the potentially high expression level of leptin receptor in gastric cancer." (PMID 33799880, 2021). "Additionally, in stomach cancer cells, cleaved caspase 3 level increased by leptin-receptor inhibition, that is, apoptosis increased." (PMID 26147886, 2015). "Therefore, further studies are required to clearly define the prognostic value of leptin-receptor expression in gastric carcinomas." (PMID 26147886, 2015). "In other words, leptin-receptor is suggested to prevent apoptosis in gastric carcinoma cells." (PMID 26147886, 2015). "Leptin-receptor may thus play a pivotal role in the progression of gastric carcinoma." (PMID 26147886, 2015). "We evaluated expression of leptin-signaling-related proteins (leptin, leptin-receptor, pSTAT3, ERK, pAkt, mTOR and HIF-1 alpha) and the EBV infection status within cancer cells, and determined their clinicopathological significance in gastric carcinomas." (PMID 26147886, 2015).
Genetic obesity (3 papers, 2015 to 2024). "In another model of genetic obesity, leptin receptor-deficient (db/db) mice, Gly-MCA administration daily for 6 weeks reduced body weight, fat mass and the fat/lean mass ratio compared with vehicle-treated mice." (PMID 26670557, 2015).